ALDH1A3 (aldehyde dehydrogenase 1 family member A3)
Diseases named in the same sentence as ALDH1A3 in open-access papers (continued):
Sharing a sentence is not in itself a finding about the gene and the disease.
breast carcinoma (continued). "Recently, it has been reported that ALDH1A3 can function as a novel marker of cancer stem cells and predict clinical prognosis in breast cancer and glioblastoma." (PMID 24345474, 2013). "Different ALDH isoforms have been shown to be important in different types of cancers, but ALDH1a3 is emerging as a potential cancer stem cell marker in breast cancer." (PMID 23088371, 2012). "Notably, dysregulated GABAergic metabolic reprogramming was found to increase the expression of ALDH1A3 and promote breast cancer metastasis." (PMID 40900801, 2025). "To investigate the mechanism of ALDH1A3‐mediated breast cancer metastasis, we assessed the effect of ALDH1A3 on the expression of proteases and the regulators of proteases that degrade the extracellular matrix, a process that is essential for invasion and metastasis." (PMID 37753740, 2024). "Further structural modification of N6 led La Motta and coworkers to identify MF7, a fluoro derivative showing a micromolar IC50 (=22.8 ± 1.6 μM) on recombinant human ALDH1A3 in enzymatic assays and antiproliferative activity in the breast cancer MDA-468 cell line in vitro." (PMID 39001459, 2024). "Finally, we investigated the effects of 2DG on the percentage of CD24−CD44+ in breast cancer cells with altered ALDH1A3 levels." (PMID 39251846, 2024). "We next investigated how ALDH1A3 affects the overall EMT score of breast cancer patient tumors." (PMID 39251846, 2024). "Given that CD24−CD44+ cells also have enhanced aerobic glycolytic activity, and ALDH1A3 decreases the CD24−CD44+ population, we hypothesized that ALDH1A3 affects the glucose metabolism of the breast cancer cells." (PMID 39251846, 2024). "Therefore, there are cancer-specific effects in terms of the role of ALDH1A3 in glycolysis and oxidative phosphorylation and we cannot generalize the effects we observe in breast cancer to other cancer types." (PMID 39251846, 2024). "Given the critical role of proteases in the degradation of the extracellular matrix, we investigated the possibility that ALDH1A3 might play a role in regulating proteases that play a role in breast cancer progression." (PMID 37753740, 2024). "Notably, amplification of ALDH1A3 was more common in TNBCs among all breast cancer subtypes, which is consistent with its increased expression in TNBCs." (PMID 36672441, 2023). "Similarly, in breast cancer cells, ALDH1A3 expression is suppressed cells through miR-7 by binding a sequence in the 3′ untranslated region (UTR)." (PMID 36672441, 2023). "Our analysis revealed that the five unique hub genes (PPARG, HIPK2, ZFP36L1, HMGB2 and ALDH1A3) may constitute a gene expression signature specifying a therapeutic response of ERβ1-expressing ERα-positive breast cancer cells to treatment with OHT+ATRA." (PMID 36835157, 2023). "Furthermore, it appears that miR-7 reduces breast cancer growth by inhibiting the activity of ALDH1A3 and diminishing the number of breast cancer stem cells." (PMID 36996494, 2023). "This suggests PKCλ may be required for symmetric and asymmetric cell propagation of ALDH1A3-positive cells and may be a key contributor to the cellular heterogeneity seen in breast cancer." (PMID 32658903, 2020). "Importantly, this association went beyond the three manipulated cell lines, as NRAD1 levels correlated with ALDH1A3 in breast cancer patient tumors and in a panel of breast cancer cell lines." (PMID 31197235, 2020). "ALDH1A3 has been reported to be a cancer stem cell marker in breast cancer." (PMID 32641986, 2020). "However, tumor sections revealed a negative correlation between serum erythropoietin levels and the number of ALDH1A3-positive cells, a marker for breast cancer-initiating cells." (PMID 30700319, 2019). "ALDH1A3 is the ALDH isoform predominantly detected in breast cancer stem cells." (PMID 30138330, 2018). "In breast cancer cell lines, ALDH1A3 influenced cancer progression via differential RA signaling." (PMID 30087899, 2018).
breast carcinoma (continued). "Eight inhibitors in this validation set (Kyneurine, Citral, Daidzin, DEAB, Disulfiram, Gossypol, Molinate and Pargyline) were recently tested by Marcato and colleagues for their ability to reduce ALDEFLUOR fluorescence in breast cancer cells that express ALDH1A3." (PMID 28129349, 2017). "While this suggests that ALDH is an important player in breast cancer metastasis; the actual functional contribution of ALDH1 (in particular its isozymes ALDH1A1 and ALDH1A3) in breast cancer metastasis requires further elucidation, and this was the goal of the current study." (PMID 28937653, 2017). "In contrast, 468ALDH1A3low and 159ALDH1A3low cells were observed to be significantly more adherent and more migratory than respective control cells (p < 0.05), suggesting that adhesion and migration of human breast cancer cells is differentially influenced by ALDH1A1 versus ALDH1A3." (PMID 28937653, 2017). "To investigate the association of c-Met with CSC markers such as ALDH1A1, ALDH1A3, CD44, and CD133 at gene expression levels in human breast cancers, we analyzed mRNA data and the clinical information of 1904 patients of breast cancers from cBioPortal for Cancer Genomics." (PMID 28966724, 2017). "The combined in vitro and in vivo data presented in this study suggests that ALDH1A1 and ALDH1A3 both contribute functionally to various steps in the breast cancer metastatic cascade; however, they may do so in different ways." (PMID 28937653, 2017). "Similarly, high c-Met expression and its activation are also suggested to be involved in the promotion of ALDH1A3 gene expression in Basal-like type of breast cancer." (PMID 28966724, 2017). "Interestingly, in one study, ALDH1A3 was found to promote or inhibit breast cancer metastasis depending on the specific epigenetic context framing retinoic acid signaling in vivo." (PMID 26445849, 2016). "We determined that subtype-specific expression of this tumor suppressor is due to both its specific hypomethylation, and ALDH1A3 expression within basal-like breast cancers, which provides its necessary transcription induction molecule, RA, for nuclear hormone receptor RARα." (PMID 27286452, 2016). "Moreover, several ALDH isoenzymes were associated to TICs properties, such as ALDH1A1 in melanoma and lung adenocarcinoma, ALDH1B1 in colon cancer, ALDH1A3 in breast cancer and NSCLC, and ALDH7A1 in prostate cancer." (PMID 27724856, 2016). "ALDH1A3 may promote progress and metastasis of various cancers, such as prostate cancer, gallbladder cancer, breast cancer, ovarian cancer and NSCLC, as well as gastric cancer in our study, and be identified as the biomarkers for poor prognosis." (PMID 27015121, 2016). "Based on various studies, it appears that the ALDH family has 19 isoforms that are expressed to a greater extent in the cancer of specific areas of the body; for example ALDH1A3 isoform in breast cancer, ALDH7A1 isoform in prostate cancer, and ALDH1A1 in pancreatic cancer." (PMID 28008389, 2016). "Moreover, ALDH1A3 significantly upregulated in the plasma of breast cancer patients, especially in TNBC when compared with normal control (Normal control vs breast cancer, p = 0.0135; non-TNBC vs TNBC, p = 0.0248)." (PMID 27842518, 2016). "ALDH1A3 has been found to play a role as a predictor of metastasis in breast cancer." (PMID 25969992, 2015). "For example, expression of the ALDH1A3 has been experimentally shown to modulate survival of melanoma and glioma cell subpopulations exhibiting properties of cancer stem cells and to promote pro-tumorigenic features in breast cancer cells." (PMID 25868979, 2015). "However, ALDH1A3 expression has been shown to correlate better with aldehyde activity in breast cancer stem cells than ALDH1A1 expression, and correlate with tumor grade, stage and metastasis." (PMID 24053169, 2013).
breast carcinoma (continued). "Therefore, future research studying breast cancer stem cells should incorporate ALDH1A3 expression in order to determine its role as a potential marker of cancer stem cell activity." (PMID 22280212, 2012). "Additionally, ALDH1A3, a key member of the ALDH family, is closely associated with development, progression, radioresistance and prognosis in a variety of cancers including adenocarcinoma, poorly differentiated breast cancer and high-grade glioma." (PMID 36996494, 2023). "In breast cancer, ALDH1A3-mediated effects on gene expression changes and tumor growth could be mimicked with RA treatment, which suggested that at least a part of ALDH1A3′s cancer-promoting effects could be due to its production of RA and the RA-mediated gene expression changes." (PMID 36672441, 2023). "Interestingly, Pan and colleagues reported that miR‐7 could inhibit breast cancer growth by suppressing ALDH1A3 with accompanying decrease in the breast cancer stem cell population." (PMID 35579852, 2022). "On the other hand, PDSs generated from breast cancers with associated lymph nodes (LN) metastasis were characterized by higher expressions of the EMT marker FOSL1 (p = 0.047) and the breast CSC-related gene ALDH1A3 (p = 0.024), when MCF7 or T-47D cell lines were used as reporters, respectively." (PMID 35565301, 2022). "Likewise, expression of the ALDH1 isoform ALDH1A3 in patient breast tumor samples was significantly correlated with tumor grade, metastasis and cancer stage suggesting ALDH1A3 as a novel prognostic marker for breast cancer stem/ initiating cells." (PMID 32430004, 2020). "Alternate functions of ALDH1A3 may contribute to breast cancer progression and stem-cell activity." (PMID 29192143, 2017). "Among the ALDH isoforms present in breast cancer, members of the ALDH1 family, including ALDH1A1 and ALDH1A3, contribute to cancer stemness, progression, and resistance." (PMID 40076923, 2025). "Gene expression correlation analysis revealed that USP30 negatively correlates with the expression of stem cell markers such as MMP2, MMP9, MYC, OCT4(POU5F1), NANOG, ALDH1A3, CD133 (PROM1), EPCAM, CD24, and ITGA6 in breast cancer cohorts." (PMID 41306556, 2025). "We calculated the EMT score of breast cancer patient tumors from TCGA BRCA and METABRIC datasets grouped as having low ALDH1A3 levels (bottom third of patient tumors) versus high ALDH1A3 (top third of patient tumors)." (PMID 39251846, 2024). "In exploring to potential relationships between ALDH1A3 and uPA and PAI‐2 in breast cancer patients, we also performed individual analyses of these proteins in fixed breast cancer patient tumour samples." (PMID 37753740, 2024). "Aldehyde dehydrogenase 1A3 (ALDH1A3) regulates expression of tissue plasminogen activator (PLAT/tPA), leading to increased invasion and metastasis of breast cancer cells." (PMID 37753740, 2024). "Among the members of the ALDH1 family, ALDH1A1 and ALDH1A3 have a much more dominant role in upregulating ALDH1 activity, potentially resulting in a poor prognosis in breast cancer." (PMID 39796106, 2024). "The mixed decreased migration/increased invasion ALDH1A3-induced phenotypic changes, and the impact of ALDH1A3 on both EMT and MET markers, suggest that ALDH1A3 is a key player in determining the plastic hybrid EMT-MET state in breast cancer." (PMID 39251846, 2024). "For breast cancer, ALDH activity and ALDH1A3 are highest in the aggressive triple-negative breast cancer (TNBC) subtype." (PMID 39251846, 2024). "Separating by subtype, we noticed the same trends of ALDH1A3 levels correlations with EMT scores in ER+, HER2+, and TNBC, especially in ER+ breast cancers." (PMID 39251846, 2024). "In breast cancer cell lines with high ALDEFLUOR activity, such as MDA-MB-468 cells, ALDH1A3 knockdown significantly decreased the ALDEFLUOR-positive rate, whereas ALDH1A1 knockdown did not have this effect." (PMID 36651035, 2023).
breast carcinoma (continued). "Altogether, these findings demonstrate the significance of ALDH1A1, ALDH1A3, and ALDH2 inhibition as potential therapeutic targets in breast cancer." (PMID 37686694, 2023). "Despite silico-derived data being obtained from a small number of patients, we were able to identify ALDH1A3, MED20, PABPC4, SLC26A11 and SCP2 as deregulated genes in diabetic breast cancer patients, which coincided with our microarray data." (PMID 37511575, 2023). "Citral, which is a natural product, shows potent inhibitory activity against ALDH1A1, ALDH1A3, and ALDH2 in breast cancer cells." (PMID 36694633, 2023). "ALDH1A3 and RA induce lncRNA non-coding RNA in the aldehyde dehydrogenase 1A pathway (NRAD1), formerly known as LINC00284 in breast cancer." (PMID 36672441, 2023). "We also evaluated the expression of ALDH1A3 and CD44, markers for breast cancer stem cells, in both control and RAB4A knockdown cells, and in the RAB4A knockdown cells that concurrently express either RAC1WT or RAC1CA." (PMID 36307864, 2022). "The elimination of ALDH1A1, ALDH1A3 inhibits ALDH1 activity, increases chemosensitivity, and reverses chemoresistance in breast cancer." (PMID 36387165, 2022). "Breast cancer patient datasets from TCGA, METABRIC and GEO were used to assess the co-expression of GABA pathway genes with ALDH1A3." (PMID 34989902, 2022). "In addition, ALDH1A3 expression has been correlated with poor prognosis in breast cancer, chemoresistance of mesothelioma and radioresistance of head and neck cancer, and its inhibition has been proven to induce the cytotoxicity of those cancer cells that present an ALDH1A3 overexpression." (PMID 34641313, 2021). "In breast cancer patient tumor samples and in a panel of cell lines, LINC00162 levels did correlate with ALDH1A3 mRNA; however, to a decreased degree than NRAD1." (PMID 31197235, 2020). "The ALDH1A3 isotype has been reported to be responsible for ALDH activity in cardiomyocyte, breast cancer, and cholangiocarcinoma cells." (PMID 32977608, 2020). "Both ALDH1A3 and treatment with ATRA promoted the expression of RA-inducible genes in MDA-MB-231, MDA-MB-468, and MDA-MB-435 breast cancer cell lines." (PMID 30733805, 2019). "High expression of c-Met (MET+) correlated with expression of CSC markers, ALDH1A1 (p < 0.001), ALDH1A3 (p < 0.001), and CD133 (p < 0.001) in breast cancers." (PMID 28966724, 2017). "Expression of ALDH1A1 or ALDH1A3 was knocked down in MDA-MB-468 and SUM159 human breast cancer cells using siRNA." (PMID 28937653, 2017). "siRNA was used to knockdown expression of two ALDH1 isozymes (ALDH1A1 and ALDH1A3) in MDA-MB-468 and SUM159 breast cancer cells and generate the following cell populations: 468CON, 468ALDH1A1low, 468ALDH1A3low, 159CON, 159ALDH1A1low, and 159ALDH1A3low." (PMID 28937653, 2017). "Overall, the results of this study support the concept that ALDH1 plays a functional role in both breast cancer metastasis and therapy resistance; although the ALDH1A1 and ALDH1A3 isozymes seemed to contribute to these behaviors in different ways." (PMID 28937653, 2017). "High expression of c-Met strongly correlated with the expression of two CSC markers, ALDH1A3 and CD133 in breast cancers." (PMID 28966724, 2017). "ALDH1A3, which is the dominant isoform of ALDH, is significantly upregulated in breast cancer plasma especially in TNBC (p = 0.0248)." (PMID 27842518, 2016). "These correlations between ALDH1A3 and RARRES1 suggests that expression of RARRES1 in breast cancer is not only controlled by methylation in the promoter region, but also by ALDH1A3 via its production of RA." (PMID 27286452, 2016). "In breast cancer CIC, the ALDH1A3 isotype predominates and is predictive of metastasis, while in prostate cancer the ALDH7A1 isotype predominates." (PMID 24086346, 2013). "Moreover, knocking down these two isoenzymes, ALDH1A1 and ALDH1A3, resulted in decreased ALDH activity, leading to decreased therapy resistance and metastatic behavior in breast cancer cells." (PMID 39796106, 2024).
breast carcinoma (continued). "In breast cancer, the effects of ALDH1A3 were not as clear, with ALDH1A3 promoting tumor growth in two triple-negative breast cancer cell lines (MDA-MB-231 and MDA-MB-435 cells) but inhibiting in a third (MDA-MB-468 cells)." (PMID 36672441, 2023). "Furthermore, it has been shown that NANOG signaling increases ALDH1A3 activity by activating the NOTCH1 and AKT pathways, which stimulates DNA double-strand break repair capability and confers radio-resistance to breast cancer cell lines." (PMID 37686694, 2023). "In contrast, the same study showed that diadzin, chloral hydrate, coprine, gossypol, and pargyline did not inhibit ALDH1A3 activity of breast cancer cells even at 100 μM concentrations." (PMID 36672441, 2023). "The expression of key markers associated with proliferation (MKI67, PCNA, CCNB1, MYBL2, BUB1, CCND1), apoptosis (BCL2, CASP7, CASP8, CASP9, CASP3, BAX, APAF1), differentiation (CDH1, CD24, EPCAM, ESR1, NGFR, RUNX1), and breast cancer stemness (CD44, ITGA6, DNER, ALDH1A3, ABCG2, PROCR) was assessed." (PMID 35183258, 2022). "In breast cancer patient datasets (TCGA, Cell 2015 and METABRIC), expression of ABAT was negatively correlated while expression of GABRE was positively correlated with ALDH1A3 expression, consistent with the MDA-MB-231 data." (PMID 34989902, 2022). "Moreover, miR-203 and miR-150 can regulate the expression of DNMT3A and DNMT3B in breast cancer cells, resulting in regulation of CD44, ALDH1A3, OCT3/4, SOX2 expression, which are critical for breast cancer stem cell development." (PMID 35620052, 2022). "Human U87MG glioblastoma and human HCT116 colorectal cancer are labelled as ALDH1A3+ cell lines, HEK293T as ALDH1A2+ cell line, human foetal astrocytes (hASTRO) and CCD-18Co human colon fibroblasts as ALDH1A1+ cell line and 4T1 mammary carcinoma as triple negative ALDH1A subfamily." (PMID 33478031, 2021). "Moreover, ALDH1A3 downregulation has been found to reduce CD44 and epithelium-specific antigen, as well as CSCs isolated from breast cancer." (PMID 34641313, 2021). "Unlike PKCλ, however, PKCζ did not correlate with ALDH1A3 in basal-like breast cancer (p = 0.191, χ2-test)." (PMID 32658903, 2020). "Using the MDA-MB 157 and MDA-MB 468 human basal-like breast cancer cell lines, we observed that levels of PKCλ and ALDH1A3 expression were higher in both breast cancer cell lines than in human normal-like (non-transformed) MCF10A cells." (PMID 32658903, 2020). "In basal-like breast cancers, ALDH1A3 expression predominates, and expression of ALDH1A3, but not ALDH1A1, correlates significantly with cancer type, tumor grade and metastasis in breast cancer." (PMID 32658903, 2020). "Moreover, PKCλ correlated with ALDH1A1 and ALDH1A3 in basal-like breast cancer (ALDH1A1; p = 0.017; ALDH1A3; p = 0.016, χ2-test)." (PMID 32658903, 2020). "ALDH1A3 has been reported to be the most important ALDH isoform responsible for ALDH activity in breast cancer cells, representing a marker of poor prognosis in breast cancer patients and correlating with increased ALDH activity in tamoxifen-resistant cells." (PMID 30622340, 2019). "For instances, a large part of breast cancer cells shows higher level of ALDH1A3, consistent with a previous report claiming ALDH1A3 to be the main contributor in ALDEFLUOR assay in breast cancer, whereas liver cancer and kidney cancer show high level of ALDH1A1." (PMID 30220009, 2019). "Despite a lack of correlation between Glo1 and ALDH1A3 expression, a major population of patients with basal-like breast cancers highly expressed both Glo1 and ALDH1A3 (n = 70 of 199)." (PMID 30559934, 2018). "To test the hypothesis, we first compared the expression of KLF4, ALDH1A1, ALDH1A3, CD44, and CD24 in human breast cancer samples available in TCGA database." (PMID 30038266, 2018).